EFCAB6 (EF-hand calcium binding domain 6)
Description:
Negatively regulates the androgen receptor by recruiting histone deacetylase complex, and protein DJ-1 antagonizes this inhibition by abrogation of this complex. Microtubule inner protein (MIP) part of the dynein-decorated doublet microtubules (DMTs) in cilia axoneme, which is required for motile cilia beating (By similarity).
Synonyms: DJBP; KIAA1672; FLJ23588; HSCBCIP1; dJ185D5.1
Tractability: PROTAC: its protein half-life has been measured.
Gene: Protein-coding gene on chromosome 22 (43,528,744 to 43,812,337, reverse strand). Ensembl gene ENSG00000186976.
Subcellular location: Nucleus; Cytoplasm, cytoskeleton, flagellum axoneme
Subcellular location (Human Protein Atlas): Nucleoplasm; Mid piece; Principal piece
Gene Ontology:
Molecular function: calcium ion binding
Biological process: androgen receptor signaling pathway; flagellated sperm motility; response to testosterone
Cellular component: nucleoplasm; nucleus; sperm flagellum; axonemal A tubule inner sheath
Genetic constraint (gnomAD): Loss-of-function variants: 133 observed, 151.6 expected, observed/expected ratio (o/e) 0.88, 90% interval 0.76 to 1.01. The upper end of that interval is the gene's LOEUF score, 1.01, which puts it in group 4 of 6, group 1 being the genes least tolerant of losing a copy. Missense variants: 1,646 observed, 1,760.2 expected, observed/expected ratio (o/e) 0.94, 90% interval 0.9 to 0.97. Synonymous variants: 644 observed, 654.52 expected, observed/expected ratio (o/e) 0.98, 90% interval 0.92 to 1.05.
Homologues: Orthologues: chimpanzee EFCAB6 (99% identical), macaque EFCAB6 (93% identical), dog EFCAB6 (77% identical), guinea pig EFCAB6 (67% identical), mouse Efcab6 (66% identical), rat Efcab6 (65% identical), Drosophila melanogaster TpnC73F (2% identical), Drosophila melanogaster TpnC47D (2% identical), Drosophila melanogaster TpnC41C (1% identical). Paralogues in human: CAPS2 (6% identical), SPATA21 (5% identical), PHF24 (4% identical), CAPSL (3% identical), CAPS (2% identical).
Diseases named in the same sentence as EFCAB6 in open-access papers:
EFCAB6 is named in the same sentence as 9 diseases in open-access papers, as found by Europe PMC text mining. Sharing a sentence is not in itself a finding about the gene and the disease. The quoted sentences say what the papers report.
cholesteatoma (1 paper, 2023). A pathologic process characterized by the proliferation of keratinizing squamous epithelium resulting in the accumulation of keratin and cells in the middle ear and/or mastoid. "Variants in LY75-CD302, EFCAB6, HRASLS, and UBP with approximately 50% variant allele frequencies (VAF) could be somatic variants acquired before cholesteatoma development." (PMID 37968650, 2023).
male infertility (1 paper, 2025). The inability of the male to effect fertilization of an ovum after a specified period of unprotected intercourse. "Previous studies have shown that high expression of Efcab6 in cells can inhibit transactivation of AR, thereby suppressing AR expression and ultimately causing male infertility." (PMID 40643461, 2025).
cancer (2 papers, 2021 to 2024). A tumor composed of atypical neoplastic, often pleomorphic cells that invade other tissues. "Using the ChIP Seq bam files, we visualized the exact genomic location of DVL-1 binding (blue peak) at various cancer-associated genes not previously designated as Wnt target genes such as TRIO, COL5A1, EXD3, OR4A47, GLDN, and EFCAB6 compared to IgG control (red peak) using IGV." (PMID 34659647, 2021). "Some downregulated genes (EHF and MMP14), mainly involved in proliferation and cancer development, were not restored upon EZH2 inhibitor treatment, and some that were upregulated in KO samples retained or even increased their high expression after treatment (EFCAB6 and CDKN2A)." (PMID 38672463, 2024).
heart diseases (1 paper, 2015). "Efcab6 encodes for EF-hand calcium binding domain 6 and belongs to the large and diverse calcium regulating EF-hand superfamily; the EF-hand calcium binding motif was identified with functional importance in heart diseases in earlier studies." (PMID 25646840, 2015).
EFCAB6 also shares sentences with these, for which no sentence is quoted: asthenozoospermia (1 paper); COFS syndrome (1); infertile (1); left ventricular hypertrophy (1); schizophrenia (1).